INPP4B (inositol polyphosphate-4-phosphatase type II B)
Diseases named in the same sentence as INPP4B in open-access papers (continued):
Sharing a sentence is not in itself a finding about the gene and the disease.
skin cancer (2 papers, 2023 to 2025). "Conversely, NK inactivation genes including Itga1 (Cd49a), Inpp4b, Tnfsf10, Il7r, and Cxcr6 dramatically decreased in skin tumors." (PMID 40282557, 2025). "Some of these gene products, including Akt, PI3K p110α, PTEN, and inositol polyphosphate 4-phosphatase type II (INPP4B), have been reported in cancers including skin cancer." (PMID 37371141, 2023).
type II diabetes (2 papers, 2021 to 2024). "When fed high fat diet, Inpp4b−/− males develop type II diabetes, inflammation of adipose tissue, and prostate neoplasia." (PMID 33772116, 2021).
autoimmune disease (1 paper, 2025). A disorder resulting from loss of function or tissue destruction of an organ or multiple organs, arising from humoral or cellular immune responses of the individual to their own tissue constituents. "Given that PI3K signalling pathway has been implicated in the pathogenesis of several autoimmune disorders, including rheumatoid arthritis (RA) and MS, our study raises the possibility that INPP4B may also play a protective role in autoimmune contexts." (PMID 40754682, 2025). "Future studies are warranted to explore whether altered INPP4B expression or function contributes to the process of autoimmune diseases, and whether restoring INPP4B activity may represent a novel therapeutic strategy to prevent inappropriate T‐cell activation in autoimmune settings." (PMID 40754682, 2025). "In this context, INPP4B may act as a brake on PI3K‐driven T‐cell activation and differentiation, suggesting that its modulation towards PI3K activity could influence T‐cell activity and autoimmune disease progression." (PMID 40754682, 2025).
bladder urothelial carcinomas (1 paper, 2018). "Together, CoxPH SubID analysis identified three previously unreported contexts where INPP4B expression status was shown to be prognostically important: kidney clear cell, liver hepatocellular, and bladder urothelial carcinomas." (PMID 29415082, 2018).
cervical adenocarcinoma (1 paper, 2018). An adenocarcinoma arising from the cervical epithelium. "For cervical adenocarcinoma samples, 15 of 49 (30.6%) had positive INPP4B staining (also largely in the cytoplasm) and 34 of 49 (69.4%) negative staining." (PMID 29516642, 2018).
diabetes (1 paper, 2021). "In this report, we show that INPP4B is a key regulator of metabolic health in lean male mice and protects obese mice from diabetes and prostate neoplasia." (PMID 33772116, 2021).
extramedullary plasmacytoma (1 paper, 2021). "We further examined INPP4B levels in the extramedullary plasmacytoma (EMP) tissues and human MM cell lines." (PMID 35070988, 2021). "Thirty-five extramedullary plasmacytoma patients expressed undetectable INPP4B." (PMID 35070988, 2021). "Seven extramedullary plasmacytoma patients expressed INPP4B reversible focal positive." (PMID 35070988, 2021). "In this study, we evaluated the expression of INPP4B in 28 cases of newly diagnosed MM patients and 42 cases of extramedullary plasmacytoma (EMP) patients compared with normal plasma cells and found that low INPP4B expression was correlated with poor outcomes in MM patients." (PMID 35070988, 2021).
glioblastoma (1 paper, 2023). The most malignant astrocytic tumor (WHO grade IV). "High levels of the calcium-binding protein 1 (CABP1), as detected after INPP4B overexpression in etoposide-resistant RB355 cells, were likewise revealed by Kaplan–Meier analysis of glioblastoma hub genes and was negatively associated with relapse-free survival of glioblastoma patients." (PMID 36993823, 2023).
Infertility (1 paper, 2020). "Within the infertile population, INPP4B expression was significantly lower in the group lacking spermatids." (PMID 32413098, 2020).
Insulin resistance (1 paper, 2021). Increased resistance towards insulin, that is, diminished effectiveness of insulin in reducing blood glucose levels. "Lower levels of Inpp4b mRNA were also detected in the pancreas and liver, indicating that Inpp4b is expressed in all major organs involved in insulin resistance." (PMID 33772116, 2021). "To determine whether insulin resistance in Inpp4b−/− mice is associated with NAFLD, we first compared the liver weights in WT and Inpp4b−/− males fed with LFD or HFD." (PMID 33772116, 2021).
mesenchymal tumors (1 paper, 2022). "We also compared the protein level data and found that PI3K pathway activators like TSC1, 4EBP1 and p4EBP1, PI3K-p85, RICTOR-pT1135 were significantly increased in high mesenchymal tumors, and PI3K inhibitor like LKB1 and INPP4B expression was significantly decreased." (PMID 36120580, 2022).
metastatic prostate carcinoma (1 paper, 2014). A carcinoma that arises from the prostate gland and has spread to other anatomic sites. "INPP4B is preferentially lost in advanced and metastatic prostate cancer characterized by increased local invasion of tumor cells." (PMID 25248616, 2014).
myeloid leukemia (1 paper, 2018). A clonal proliferation of myeloid cells and their precursors in the bone marrow, peripheral blood, and spleen. "To confirm our theory, we then assessed INPP4B mRNA and protein abundance across a panel of human myeloid leukemia cell lines." (PMID 29343273, 2018).
Obesity (1 paper, 2021). Accumulation of substantial excess body fat. "The highest protein levels of CD68 were observed in the eWAT of the HFD Inpp4b−/− group, suggesting that the INPP4B deficiency promotes the inflammatory response of adipose tissue in diet-induced obesity." (PMID 33772116, 2021). "HFD Inpp4b−/− males were significantly more susceptible to obesity-induced neoplastic transformation of the prostate than the WT males." (PMID 33772116, 2021). "INPP4B expression protects the liver from steatosis, mediates insulin sensitivity, and links obesity to neoplastic changes in the prostate epithelium." (PMID 33772116, 2021).
ovarian tumors (1 paper, 2015). "However, INPP4B loss has been found in 40% of ovarian tumors revealing the clinical significance of INPP4B and its potential use as a biomarker of PARP inhibitor response for a broadened patient subset." (PMID 25868852, 2015).
pancreatic adenocarcinoma (1 paper, 2018). "Furthermore, the prognostic significance of INPP4B in pancreatic adenocarcinoma was validated in two additional independent pancreatic adenocarcinoma datasets." (PMID 29415082, 2018).
retinoblastoma (1 paper, 2023). A malignant tumor that originates in the nuclear layer of the retina. "Fittingly, in the study presented, we demonstrated that compared to the healthy human retina INPP4B mRNA expression levels are significantly decreased in RB cell lines, indicating a tumor-suppressing role of INPP4B in retinoblastoma." (PMID 36993823, 2023). "Thus, recent studies reporting on INPP4B-mediated activation of SGK3 depict INPP4B as an oncogenic driver, whereas our functional studies indicate a tumor suppressive role of INPP4B in retinoblastoma." (PMID 36993823, 2023). "INPP4B is controversially discussed as a tumor suppressor and an oncogenic driver in various cancers, but its role in retinoblastoma in general and chemoresistant RB in particular is yet unknown." (PMID 36993823, 2023).
squamous cell cervical carcinoma (1 paper, 2018). "Among squamous cell cervical carcinoma samples, 39 of 100 (39%) had positive cytoplasmic INPP4B staining and 61 of 100 (61%) negative staining." (PMID 29516642, 2018).
thyroid tumours (1 paper, 2017). "Inpp4b ablation in Pten+/− mice promotes AKT2-dependent thyroid tumour growth." (PMID 28082369, 2017).
tongue squamous cell carcinoma (1 paper, 2025). A squamous cell carcinoma that arises from the tongue. "The tumor-promoting mechanisms of miR-765 involve multiple targets, including inositol polyphosphate 4-phosphatase type II (INPP4B) and interactions with LINC00511/Laminin Subunit Gamma 2 (LAMC2) in tongue squamous cell carcinoma." (PMID 40918504, 2025).
Waardenburg syndrome (1 paper, 2022). A disorder characterized by varying degrees of deafness and minor defects in structures arising from neural crest, including pigmentation anomalies of eyes, hair, and skin. "Six new genes were associated with NSHI: INPP4B, CCDC141, MYO19, DNAH11, SOX9, and POTEI; and one new gene, PAX8, was associated with Waardenburg syndrome." (PMID 35440622, 2022).
tumor (100 papers, 2011 to 2025). "The loss of INPP4B expression has been consistently linked to a more aggressive tumor phenotype and poor prognosis, underscoring its potential as a robust prognostic indicator." (PMID 38172946, 2024). "Taken together, the loss of INPP4B in the prostate leads to overlapping and distinct changes in tumor suppressor and oncogenic downstream signaling." (PMID 38001678, 2023). "Altered levels of INPP4B expression have been linked to cancer progression in various human tumor types." (PMID 36147923, 2022). "INPP4B has been identified as a tumor suppressor often associated with PTEN in several cancers, and loss of INPP4B protein has also been correlated with reduced patient survival." (PMID 33922652, 2021). "In the present study, we first revealed that INPP4B is highly expressed in GBC tissues compared with non-tumour tissues and is associated with the prognosis of GBC patients in different histopathological differentiation groups." (PMID 33879096, 2021). "INPP4B expression was associated with tumour-node-metastasis (TNM) stage and histopathological differentiation." (PMID 34729121, 2021). "Kofuji's work further discovered that in PTEN deficiency, INPP4B acts as tumor suppressor with very important functions." (PMID 31595147, 2019). "Loss of INPP4B was linked with advanced tumor grade, larger tumor size, a loss of hormone receptors and aggressive tumors." (PMID 30871273, 2019). "Altered levels of INPP4B expression have been linked with cancer progression in various different human tumour types." (PMID 31695845, 2019). "Given the numerous contrasting models for INPP4B function in cancer, we investigated both deficiency and overexpression to elucidate predominant tumour suppressor or oncogenic roles, respectively in MEF." (PMID 31695845, 2019). "Loss of Pten, Pipp or Inpp4b expression or function promotes tumour growth in murine cancer models through enhanced AKT isoform-specific signalling." (PMID 28082369, 2017). "To identify xenografts models with tumor suppressor loss and to determine the frequency of concomitant loss of INPP4B and PTEN proteins, we analyzed PTEN and INPP4B expression by immunohistochemistry (IHC)." (PMID 27374081, 2016). "Using a two-class (human basal-like versus human non-basal) Fisher's exact test, we identified 29 DNA copy-number gains or losses commonly enriched in human basal-like tumor genomes (P-value<0.05), which included gains of Met and Cul4a and loss of Inpp4b." (PMID 27149990, 2016). "Deficiency in INPP4B caused significant retardation of tumour growth in vivo, which was associated with reduction in SGK3 activation." (PMID 26573229, 2015). "Low INPP4B expression was associated with larger tumor size (P = 0.035) and higher nuclear grade (P = 0.031), compared to high expression." (PMID 25542038, 2014). "Further functional studies are needed to determine whether the observed trends in PTEN and INPP4B mutations translate into differential tumor behavior or therapeutic responses." (PMID 40282485, 2025). "We investigated whether this might be due to the activation of compensatory mechanisms triggered by the loss of INPP4B that opposes tumor progression." (PMID 38001678, 2023). "Interestingly, PIK3CA mutations frequently co-occur with PTEN mutations or INPP4B overexpression, which accelerate tumor development." (PMID 37471270, 2023). "In addition, high INPP4B expression was associated with a favourable prognosis in patients with high-moderately differentiated tumours, while poor prognosis was observed in patients with low-undifferentiated tumours." (PMID 33879096, 2021). "INPP4B loss has been considered a marker of aggressiveness in TNBC tumours." (PMID 32211045, 2020). "However when Inpp4b loss was combined with Pten heterozygosity, it altered the penetrance of the Pten-spectrum of tumours, and notably malignant thyroid cancer was observed." (PMID 31695845, 2019).
tumor (continued). "Waterfall plot analysis comparing tumor volumes at start and treatment end point revealed great reduction of tumor volumes in the olaparib-treated INPP4B-deficient cohort in contrast to the control cohort, which exhibited little to moderate response to treatment." (PMID 25868852, 2015). "Thus it has been suggested that INPP4B may be a tumour suppressor in the context of PTEN loss, and may have weak tumour suppressive function otherwise." (PMID 31695845, 2019). "Two key tumor suppressors—inositol polyphosphate 4-phosphatase type II (INPP4B) and phosphatase and tensin homolog (PTEN)—regulate PIP3 through dephosphorylation." (PMID 40804731, 2025). "Similar to the benign LTT group, INPP4B expression was increased in the tumor samples (log2FC = 1.1, p = 0.01)." (PMID 40729351, 2025). "Among the markers elevated in the LTT group of benign samples and cancer samples, INPP4B, known for its dual role in cancer biology, functions as both an oncogene and tumor suppressor." (PMID 40729351, 2025). "Functionally, INPP4B acts as a tumor suppressor by exerting negative regulation on PI3K signaling, a signaling cascade crucial for controlling cell proliferation, survival, and metabolism." (PMID 38172946, 2024). "Rigorous studies have explored the correlation between INPP4B expression levels and various clinicopathological features, such as tumor grade, hormone receptor status, and HER2 amplification." (PMID 38172946, 2024). "The DEG in the ‘inositol’ group with the highest fold change is INPP4B, recently discovered by our group as a tumor suppressor gene in chemotherapy-resistant RBs." (PMID 39695086, 2024). "We demonstrated that INPP4B overexpression reduces anchorage-independent growth of etoposide-resistant RB cell lines, reflecting its tumor suppressive function." (PMID 36993823, 2023). "By contrast, INPP4B depletion in melanocytes leads to a delay in tumor development in vivo, suggesting a tumorigenic capacity of INPP4B in this setting." (PMID 36993823, 2023). "Nevertheless, further functional experiments will be required to unravel the interplay between INPP4B and the identified differentially expressed genes in terms of tumor suppressive as well as oncogene-like impacts." (PMID 36993823, 2023). "Caspase-3/7-mediated apoptosis was concomitantly increased, suggesting a tumor suppressive role of INPP4B in chemoresistant RB cells." (PMID 36993823, 2023). "Functions mediated by the verified upregulated interferon-induced protein with tetratricopeptide repeats (IFIT) and the downregulated epithelial membrane protein 1 (EMP1) are in line with the tumor suppressive function of INPP4B seen in RB cells." (PMID 36993823, 2023). "Originally, INPP4B was described as a tumor suppressor gene in various cancers, but it is now controversially discussed as an oncogenic driver (for review see:)." (PMID 36993823, 2023). "Low INPP4B levels have been reported in various cancers and neoplasms, suggesting a tumor suppressor function in these tumor entities." (PMID 36993823, 2023). "Our RNAseq data indicated that INPP4B overexpression in etoposide resistant RB cells led to several gene expression changes, potentially related to tumor progression." (PMID 36993823, 2023). "We identified adenylate cyclase type 3 (Adcy3) and inositol polyphosphate 4‐phosphatase type II (Inpp4b), which affect tumor growth and metastatic potential, respectively." (PMID 35075772, 2022). "We next determined how Adcy3 and Inpp4b in vivo tumor growth and in vivo metastatic potential using siRNA knockdown technology." (PMID 35075772, 2022). "It is considered a tumor suppressor, as low expression of INPP4B can promote tumor growth through activation of the PI3K/AKT pathway." (PMID 36147923, 2022). "In vivo studies showed INPP4B as potentially involved in metastasis formation and therefore related to tumor aggressiveness." (PMID 35075772, 2022).
tumor (continued). "Compared to cases with favorable prognosis, the adverse-prognosis tumor samples had significantly increased expression of INPP4B, which was confirmed with traditional immunohistochemistry." (PMID 35158790, 2022). "IHC analysis showed higher INPP4B expression in normal mouse brain tissues than in tumor-burdened brain tissues." (PMID 36147923, 2022). "Together, these results show for the first time the potential role of Adcy3 in in vivo tumor growth and the involvement of Inpp4b in tumor aggressiveness and metastasis formation." (PMID 35075772, 2022). "In vivo tumor growth was determined by subcutaneously injecting Adcy3‐ or Inpp4b‐silenced 4C11+ cells into mice flank region." (PMID 35075772, 2022). "This has only been demonstrated at the cellular level in vitro so far, but we found for the first time that INPP4B plays a dual role in different tissue grades and clinical stages of the same type of tumour." (PMID 34729121, 2021). "We found that GBC patients in the high-moderate differentiation group whose tumours had high expression of INPP4B had a better prognosis, whereas those in the low-undifferentiated group had a worse prognosis." (PMID 33879096, 2021). "Here, we observed that INPP4B was highly expressed in high-moderately differentiated tumours compared with low-undifferentiated tumours (p = 0.022)." (PMID 33879096, 2021). "INPP4B is a Mg(2+)-independent phosphatase that is highly expressed in the heart, and it is a tumor suppressor involved in the inhibition of PI3K signaling." (PMID 34356046, 2021). "We found that the mean expression level of INPP4B mRNA in GC tissues was significantly lower than that in matched controls (P=0.0204); moreover, 75.68% (28/37) of the tumour tissues had a lower level of INPP4B mRNA than the matched controls." (PMID 34729121, 2021). "Inactivation of the lipid phosphatase INPP4B is frequently observed in triple-negative breast cancer, where it functions as a tumor suppressor by regulating RTK trafficking and degradation." (PMID 34298731, 2021). "To date, previous studies on the role of INPP4B as a tumour suppressor gene and oncogene, even in the same tumour, have been controversial." (PMID 33879096, 2021). "Previous studies on the role of INPP4B in tumour cells have shown that INPP4B plays different roles in different tumour cells." (PMID 34729121, 2021). "Even within the same tumour, different researchers have reached varying conclusions about the role of INPP4B as an oncogene or TSG." (PMID 33879096, 2021). "Previous studies on the role of INPP4B in tumour cells have shown that INPP4B functions as a tumour suppressor gene or oncogene in different types of tumour cells." (PMID 33879096, 2021). "qPCR and western blotting were used to investigate INPP4B mRNA and protein expression levels in paired fresh frozen tumour-normal tissue specimens." (PMID 34729121, 2021). "Actually, the tumor-promoting features of INPP4B have also been found in several cancers, and it seems that INPP4B plays complex roles in the pathogenesis of different tumors." (PMID 35070988, 2021). "When we stratified the relationship between INPP4B and the prognosis of GC in terms of tumour size, differentiation, and TNM staging, we obtained the following interesting findings." (PMID 34729121, 2021). "PIP3 levels can also be regulated by another tumour suppressor known as inositol polyphosphate-4-phosphatase type II B (INPP4B), which has the same effect as PTEN." (PMID 32211045, 2020). "INPP4B is regarded as a tumour suppressor of LC because it regulates the level of 3-phosphorylated phosphoinositide at the cellular level and activates phosphoinositide in PTEN-deficient cells." (PMID 33024640, 2020). "Inositol polyphosphate-4-phosphatase type II (INPP4B) is a dual-specificity phosphatase that acts as a tumor suppressor in multiple cancers." (PMID 32413098, 2020).